GRHL3 (grainyhead like transcription factor 3)
Diseases named in the same sentence as GRHL3 in open-access papers (continued):
Sharing a sentence is not in itself a finding about the gene and the disease.
tumor (26 papers, 2014 to 2025). "Next, associations of GRHL3 RNA and protein expression with clinicopathological characteristics including tumor stage, histological grading, and nodal status were determined by applying the Fisher exact test in the context of subtype‐specific cohorts." (PMID 38429970, 2024). "We demonstrated that loss of GRHL3 expression was abundant and associated with increased tumor stage and unfavorable prognosis in squamous bladder cancers." (PMID 38429970, 2024). "The tumor‐suppressive function of GRHL3 in the skin has been linked with the transcriptional regulation of the direct GRHL3 target gene PTEN to control the PI3K/mTOR pathway." (PMID 38429970, 2024). "Overexpression in urothelial EJ28 and J82 cells drives oncogenic features, whereas squamous‐differentiated SCaBER cells cause opposite, that is, tumor‐suppressive, functions mediated by GRHL3." (PMID 38429970, 2024). "The transcription factors IRF6 and GRHL3 are both CLP-associated candidate genes as well as prominent tumor suppressors as described in this in vitro study." (PMID 36457487, 2022). "GRHL3 is a factor associated with a tumor, of which the molecular mechanism remains a further investigation." (PMID 34888136, 2021). "This demonstrates that GRHL3 loss alone is sufficient for tumour initiation, and that its loss in the epidermis provides a potent stimulus for the development of spontaneous and chemically-induced aggressive skin SCC." (PMID 28654000, 2017). "Here, we determined GRHL3 mRNA and protein expression considering more than 600 human tissue samples and 314 TCGA samples identifying high GRHL3 mRNA and protein levels associated with increased tumor stage and a trend toward shorter recurrence‐free survival in UC." (PMID 38429970, 2024). "In addition, promoting events such as the stimulation of an inflammatory response through administration of the sole tumour promoter TPA was sufficient to facilitate tumour development in Grhl3-deficient mice." (PMID 35269877, 2022). "It will be of considerable importance to determine whether CLP-associated IRF6 and/or GRHL3 variants also affect their tumor suppressive functions in vivo, and whether CLP/VWS patients harboring such variants might have an increased risk to develop certain types of carcinomas later in their lives." (PMID 36457487, 2022). "The S-phase tumour cells with high APOBEC3A expression were all designated a binary GRHL3 activity score of ‘on’, suggesting that GRHL3 can drive APOBEC3A expression in tumour cells undergoing DNA replication, potentially causing APOBEC3A-mediated mutagenesis." (PMID 39548236, 2025). "In turn, for sq‐BLCA we revealed a strong inverse correlation between GRHL3 expression and tumor stage (P = 0.036, r = −0.258)." (PMID 38429970, 2024). "Nevertheless, genes such as Nell2, Smarca1, Slc6a14 and Grhl3 which were highly downregulated by the combined treatment were reported to contribute to tumor progression." (PMID 39450263, 2024). "The impact of GRHL3 on wound healing and cell migration was first described in epidermis, and modulated cell adhesion potential of tumor cells triggered by GRHL3 was demonstrated." (PMID 38429970, 2024). "Loss of GRHL3 expression was first described in SCC of the skin associated with tumor‐suppressive properties." (PMID 38429970, 2024). "Since tumour suppressor gene PTEN is a direct regulatory target of GRHL3, GRHL3 has a positive regulatory effect on it in vivo and can regulate the occurrence and development of tumours by activating the PI3K/Akt pathway." (PMID 37009715, 2023). "Previous studies have shown that GRHL3 can inhibit tumor growth and development in ESCC, while NECTIN4 and FZD2 play a role as cancer-promoting genes in ESCC, and no relevant report has been made on the role of other genes in ESCC." (PMID 37653730, 2023).
tumor (continued). "The screened candidates, as the targets of miR-21 and miR-21*, included a large number of oncogenic proteins and tumour suppressors, such as Ras, GRHL3, CHL1, PDCD4, PTEN, RECK and HNRPK." (PMID 35421166, 2022). "Despite this discovery, the roles of IRF6 and GRHL3 in cancers remain controversial as both factors have been described as oncogenes and tumor suppressors." (PMID 36457487, 2022). "All our results strongly suggest that IRF6 and GRHL3 act as tumor suppressors in at least the cancer tissues we analyzed." (PMID 36457487, 2022). "While some reports point towards oncogenic functions for IRF6 and/or GRHL3, others describe them as tumor suppressors." (PMID 36457487, 2022). "Results from studies in vitro and in vivo indicated that downregulation of GRHL3 expression inhibited tumor growth and metastasis and inhibited the activation of the MEK1/2 pathway." (PMID 34888136, 2021). "Suppressing the GRHL3-MEK1/2 signal axis tends to enlarge the impression of GRHL3 in tumor growth and metastasis." (PMID 34888136, 2021). "The effect of GRHL3 downexpression was the same as that of MEK1/2 antagonists on suppression of tumor growth and metastasis." (PMID 34888136, 2021). "But the U0126 reduces the tumor size of mice in both the GRHL3-KD group and the NC group, which was confirmed by histopathological examination." (PMID 34888136, 2021). "FOXO3 is a well-established tumor suppressor gene involved in various cellular processes; GRHL3 is necessary for differentiation and has a tumor-suppressing role." (PMID 34163012, 2021). "The expression of GRHL3 was notably correlated with tumor size (P = 0.037), TNM staging (P = 0.022), invasion degree (P = 0.028), and lymph node metastasis (P = 0.014)." (PMID 34888136, 2021). "Tumor growth volume was significantly smaller in GRHL3-knockdown cell-inoculated mice from the fourteenth day after injection." (PMID 34888136, 2021). "Results of the followed study in vitro and in vivo showed that downregulation of GRHL3 expression inhibited tumor growth and metastasis and inhibited the activation of the MEK1/2 pathway." (PMID 34888136, 2021). "The role of GRHL3 has been investigated in various tumor types; however, its role as an oncogene or tumor suppressor is still controversial." (PMID 33803949, 2021). "Grhl3 is normally highly expressed in the suprabasal layer, and the mechanism whereby tumours in the stem cell/basal cell compartments were initiated following loss of Grhl3 was until recently poorly understood." (PMID 31060263, 2019). "We discovered that the expression of two genes – GRHL1 and GRHL3 – is reduced in a coordinated manner in tumor samples, in comparison to the control healthy skin samples obtained from the same individuals." (PMID 29301499, 2018). "These inducible IVL-Cre driven Grhl3 cKO mice develop more tumours and at earlier time points than controls exposed to the same carcinogenesis protocol." (PMID 28654000, 2017). "We observed a significant association between increased GRHL3 mRNA expression and a higher tumor stage in urothelial but not in squamous bladder cancers." (PMID 38429970, 2024). "The GRHL3 factor also functions as a potent tumour suppressor against adult skin SCC." (PMID 35269877, 2022). "Although GRHL3 is known to function as a tumour suppressor of SCC, it remains to be seen whether this role is conserved in lung SCC and other lung cancer subtypes." (PMID 35269877, 2022). "Some studies identified IRF6 and GRHL3 as oncogenes, while others could attribute tumor suppressive functions to them." (PMID 36457487, 2022). "Next to the expression profiling, we also provide functional evidence that both IRF6 and GRHL3 are tumor suppressor genes: overexpression of IRF6 and GRHL3 in cancer cell lines impaired their proliferation, EMT, migration and induced their differentiation potential." (PMID 36457487, 2022). "Other evidence suggests a tumor suppressor function of GRHL3 in some solid tumors." (PMID 33803949, 2021).
tumor (continued). "Our results also suggested that GRHL3 mediates the tumor metastasis." (PMID 34888136, 2021). "Our preliminary data suggest that ectopic expression of GRHL3 may upregulate the tumor suppresser gene PTEN with subsequent AKT phosphorylation." (PMID 33803949, 2021). "In our study, we explored the role of GRHL3 in tumor migration and invasion and poor overall survival rate involved in progression and prognosis in CRC, which may serve as a potential target for the treatment of CRC." (PMID 34888136, 2021). "Our study suggested that GRHL3 may act as an oncogene to promote tumor growth and metastasis via the MEK pathway in CRC." (PMID 34888136, 2021). "Interestingly, that expression of GRHL3 significantly reduced in tumor tissues overexpressing SIRT1." (PMID 34163012, 2021). "Interestingly, GRHL3 also suppresses the proliferation of human keratinocytes and was shown to function as a major tumour suppressor against human SCC11,12." (PMID 30341279, 2018). "More recently, GRHL3 has been identified as a critical tumour-suppressor in head and neck SCC (HNSCC), a heterogeneous cancer associated with poor survival outcomes, and where loss of floxed Grhl3 using K14-driven Cre leads to HNSCC development in the oral cavity of these mice." (PMID 28654000, 2017). "Thus, the GRHL3–PTEN axis functions as a critical tumour suppressor pathway to prevent the onset of skin SCC." (PMID 28654000, 2017). "Co‐regulation of GRHL3 and EIF4E3, a putative tumor suppressor, was then verified by Spearman rank correlation in the TCGA BLCA data set (Spearman r = 0.257, P < 0.001)." (PMID 38429970, 2024). "Stably GRHL3‐overexpressing EJ28, J82, and SCaBER in vitro models revealed a tumor‐suppressive function in squamous and an oncogenic role in the urothelial cancer cells affecting cell and colony growth, and migratory and invasive capacities." (PMID 38429970, 2024). "Tumor-promoting roles of GRHL2 in oral squamous cell carcinoma (OSCC), esophageal, pancreatic and colorectal cancer (CRC), as well as similar roles of GRHL3 in CRC, have been summarized in a recent review." (PMID 35269877, 2022). "Deletion of the developmental transcription factor Grainyhead-like 3 (Grhl3) induces HNSCC in both humans and mice, and GRHL3 functions as a tumour suppressor against SCC of the skin through the direct transcriptional regulation of Pten." (PMID 30970654, 2019). "In HNSCC, we find evidence of GRHL3 activity and APOBEC3A in a subpopulation of tumour cells undergoing DNA replication; the context in which mutagenic APOBEC activity is postulated to occur due to deamination of lagging strand ssDNA exposed at the replication fork." (PMID 39548236, 2025). "It is important to note the limitations of performing this analysis in bulk RNA-seq data, in which APOBEC3A expression in cell types (e.g. tumour-resident macrophages or infiltrating neutrophils) that do not express GRHL3 will influence these correlations." (PMID 39548236, 2025). "GRHL3 activity and APOBEC3A expression were frequently highest near the tumour surface." (PMID 39548236, 2025). "GRHL3 expression was found to be decreased in squamous cell skin cancers (SCC) in human and tumor-bearing animals and may serve as a cancer suppressor." (PMID 34888136, 2021). "The mechanisms through which IRF6 and GRHL3 inhibit tumor development is not entirely elucidated yet and might be highly tissue-dependent." (PMID 36457487, 2022).
cancer (19 papers, 2013 to 2025). A tumor composed of atypical neoplastic, often pleomorphic cells that invade other tissues. "MiR-194 regulates GRHL3 (a gene-encoded transcription factor that suppresses cancer) and GRHL3 regulates PTEN, which ultimately leads to downregulation of PTEN levels and upregulation of p-Akt levels." (PMID 40843171, 2025). "For example, GRHL3, a TF known to stimulate migration of endothelial cells and previously linked to different types of cancers, had 19 ChIP-seq and two literature interactions with our set of 152 promoters." (PMID 39013578, 2024). "Both IRF6 and GRHL3 have been found to be implicated in regulating EMT during development as well as in cancer progression." (PMID 36457487, 2022). "For example, GRHL3 (Grainyhead-Like Transcription Factor 3) encodes a cancer suppressor that is a member of the grainyhead-like transcription factor family." (PMID 32850691, 2020). "Therefore, it can be speculated that IRF6 and GRHL3 are genetic risk factors associated with the comorbidity of cancer and CLP." (PMID 36457487, 2022). "In the urinary bladder, GRHL3 function in cancer development depends on the histological subtype and molecular background." (PMID 38429970, 2024). "In the present study, we show evidence for a dual role of GRHL3 in the context of histological and molecular subtypes of cancers arising from the urothelium." (PMID 38429970, 2024). "Lastly, GRHL3 is a surface epithelium commitment master regulator that plays a crucial role in keratinocyte cancer cell transcriptional regulation." (PMID 37853464, 2023). "Collectively, our functional assays indicate that rescue of IRF6 and GRHL3 in cancer cell lines has the potential to normalize parts of their tumorigenic phenotype by affecting proliferation, EMT, migration, and differentiation in a tissue-specific manner." (PMID 36457487, 2022). "The fact that the role of IRF6 and GRHL3 in cancer remains controversial makes this question even more challenging." (PMID 36457487, 2022). "We observed a consistent and significant downregulation of both IRF6 and GRHL3 in all the cancer cell lines analyzed compared to controls." (PMID 36457487, 2022). "Our results on reduced proliferation rate in the presence of increased levels of IRF6 and GRHL3 have been described before in cancer cell lines." (PMID 36457487, 2022). "Based on our findings, IRF6 and GRHL3 can be considered as tumor suppressor genes in various carcinomas, which makes them potential common etiological factors for cancer and CLP in a fraction of CLP-affected patients." (PMID 36457487, 2022). "To gain a better overview of published results on IRF6 and GRHL3 expression and function in cancer, we performed a literature search." (PMID 36457487, 2022). "Trying to solve this apparent conundrum, we herein aimed to characterize IRF6 and GRHL3 function in various types of carcinomas." (PMID 36457487, 2022). "GRHL3 is a relatively new protein in cancer development and got involved in various biological processes, including neural tube closure, epidermal wound healing, skin barrier formation and maintenance, cranial facial development, and control of motor activity." (PMID 34888136, 2021). "We further explored the mechanism of GRHL3 during the progress of CRC, relative to the different roles of GRHL3 in different cancers." (PMID 34888136, 2021). "The potential role of GRHL3 has been widely investigated in many different types of human tissues and cancer; however, contradictory roles of GRHL3 have been reported." (PMID 33803949, 2021). "Interestingly, GRHL3 expression differed between cancer subtypes: a significant downregulation was observed in sq‐BLCA." (PMID 38429970, 2024). "Our data uncovered consistent downregulation of IRF6 and GRHL3 in all types of carcinomas analyzed." (PMID 36457487, 2022). "However, the discrepancy concerning IRF6 and GRHL3 expression and function in carcinomas is mainly derived from studies analyzing their roles in adenocarcinomas." (PMID 36457487, 2022).
cancer (continued). "Fittingly, IRF6 and GRHL3 are frequently found dysregulated in carcinomas." (PMID 36457487, 2022). "In the current study, we aimed to clarify the role of IRF6 and GRHL3 in various human carcinomas." (PMID 36457487, 2022). "In cancer cells, FSCN1 upregulation is associated with E-cadherin downregulation, decreased cell-cell adhesion, and increased migration, prompting us to investigate the role of GRHL3 in Fscn1 regulation in wound-front keratinocytes during reepithelialization." (PMID 34494554, 2021). "Importantly, the study reveals that GRHL3 impairs migration and invasion of cancer cells, as ectopic expression of GRHL3 resulted in reduced migration and invasion capacities of T24 cells." (PMID 33803949, 2021). "Having observed strong correlations between APOBE3CA expression and GRHL3 expression and predicted activity in single-cell data from HNSCC and ESCC, we next sought to determine whether GRHL3 may be involved in regulating APOBEC3A expression cancer arising in other tissues." (PMID 39548236, 2025). "Here we demonstrate that, even though GRHL1 and GRHL3 share a high degree of sequence homology, have almost identical target DNA binding sites and display very similar expression patterns in the epidermis, the molecular mechanisms linking them to cancer are very different." (PMID 24586629, 2014). "The larger cell size and the actin stress fiber‐rich phenotype demonstrated GRHL3‐dependent cell spreading and migration during wound healing in EJ28 cancer cells." (PMID 38429970, 2024). "In contrast, GRHL3 has been reported to play an important role during MET, the reversion of the EMT process, which fits to our data in cancer cells." (PMID 36457487, 2022). "The interactions of downregulated GRHL3 in the control offspring with downregulated GPCPD1 and SNORA41 are indicative of good cancer prognosis." (PMID 28673325, 2017). "This analysis validated the identification of genes that could be specific to cancer biology, such as IL7R, JUN, NR3C1 in Ba/Sq subtype, NPAS2, FOXQ1, GRHL3 in Luminal samples, or CDKN2C, FOXJ1, MEIS2, FGFR3 in both subtypes." (PMID 36944729, 2023). "Although the role of IRF6 and GRHL3 in carcinomas is not fully elucidated yet, it is plausible to link their expression to the differentiation status of carcinomas." (PMID 36457487, 2022). "Both protein expression and mRNA expression of GRHL3 in cancer tissues were higher than those in the paired nontumorous tissues in CRC, nothing to do with the degree of neoplasma." (PMID 34888136, 2021).
adenocarcinoma (3 papers, 2021 to 2025). A common cancer characterized by the presence of malignant glandular cells. "We also observed strong correlations between APOBEC3A and GRHL3 expression (Fig. EV2D), and GRHL3 activity scores (Fig. EV2E) in bulk RNA-seq data from SCCs, and from adenocarcinomas of the cervix (CESC-AD) and oesophagus (ESCA-AD)." (PMID 39548236, 2025).
GRHL3 also shares sentences with these, for which no sentence is quoted: anencephaly (1 paper); Anxiety (1); Bartsocas Papas syndrome (1); basal cell carcinoma (1); behavioural disorders (1); breast adenocarcinoma (1); colitis (1); craniorachischisis (1); Crohn disease (1); cutaneous squamous cell carcinoma (1); cysticercosis (1); Encephalocele (1); esophageal squamous cell carcinoma (1); fibrosarcoma (1); genetic disorder (1); Granuloma (1); Hyperglycemia (1); Insulin resistance (1); lung adenocarcinoma (1); neural tube defect (1); non-melanoma skin carcinoma (1); Nonalcoholic Steatohepatitis (1); Obesity (1); prostate tumor (1); schizophrenia (1); skin disorder (1); stomach cancer (1); thyroid cancer (1); tooth agenesis (1); uterine cancer (1).